IL2 (interleukin 2)
Diseases named in the same sentence as IL2 in open-access papers (continued):
Sharing a sentence is not in itself a finding about the gene and the disease.
cancer (continued). "Because of the grave side effects of IL-2, application of IL-15 in anti-cancer immunotherapy has been extensively investigated in vitro and in vivo." (PMID 28927416, 2017). "Treatment with IL-2 has been shown to increase the population of Tregs and reduce graft-versus-host manifestations in cancer patients receiving allogeneic stem cell transplants (allo-SCT)." (PMID 28721449, 2017). "It was specifically redirected towards cancer cells by linkage of the fragment A to recombinant human interleukin-2 (IL-2), in order to target the IL-2 receptor, which is highly expressed on malignant T-cells." (PMID 28788054, 2017). "The noteworthy example supporting this notion is combination of CQ and high dose IL-2 to mitigate systemic autophagic syndrome and promote cancer cell apoptosis in animal models, yet the clinical trial of this combination treatment is still ongoing." (PMID 28629173, 2017). "We cocultured these cells with different cancer lines and analyzed IL-2 and IFNγ secretion as well as activation marker upregulation." (PMID 29085357, 2017). "Previous studies showed that in addition to it inducing the proliferation of CD8+ T cells, IL-2 preferentially stimulates short-lived effector T cells that are detrimental to cancer immunotherapy." (PMID 29123649, 2017). "The IL-2 pathway has been extensively researched and has significant clinical importance particularly with respect to transplant, cancer, and cardiovascular biology." (PMID 28750002, 2017). "Treatment with the virus was able to activate T-cells from cancer patients, as measured by increases in interleukin-2 and interferon-γ levels." (PMID 28712033, 2017). "Some studies have reported that various biomarkers, such as TNF-alpha, interleukin (IL)-1 beta, IL-6, IL-2, CRP, etc., are associated with cancer-related fatigue, although the results of these studies are not consistent in regarding this issue." (PMID 28679410, 2017). "IL-2 is an important factor in passive cancer immunotherapy that helps modulating some important immune functions." (PMID 27805072, 2017). "IL-2 is commonly used in cancer therapy as immunostimulating agent to compensate the immunosuppressive cytokines secreted by cancer cells." (PMID 28927416, 2017). "Subsequently, Tregs inhibit the differentiation and proliferation of cancer killing (cytotoxic) effector CD8+ T cells through inhibition of IL-2 production and inhibit the maturation and antigen presenting function of dendritic cells (DCs)." (PMID 29037250, 2017). "This led to the interest in both (i) using IL-2 for stimulation of autologous NK cells in cancer patients and (ii) ex vivo activation and expansion of allogeneic donor NK cells for adaptive immunotherapy." (PMID 28491060, 2017). "The application of cytokines for cancer therapy has been extensively investigated and IL-2 has traditionally been thought to hold the greatest promise, stemming from its known capacity as a T cell growth factor." (PMID 28239749, 2017). "The present review summarizes the most known cancer-related cytokines IL-2, IL-1, IL-4 and IL-6 as regulators of carcinogenesis and cancer maintenance or eradication." (PMID 28927416, 2017). "N-3 PUFAs are beneficial as a dietary supplement for cancer patients as they reduce the level of inflammatory cytokines, including IL-2, IL-6, as well as TNF-α, and promote anti-inflammatory activities." (PMID 28410575, 2017). "A computational study was carried out on cancer-related targets including IL-2, IL-6, COX-2 Caspase-3 and Caspase-8." (PMID 28344831, 2017). "Treatment with IL-2 can enhance the activity of the immune system against tumors and, by linking IL-2 to the antibody, ALT-801 can target IL-2 to cancer cells." (PMID 27974927, 2016). "The evidence for the clinical efficacy of zoledronate + IL-2 combination treatment in cancer clinical trials is however limited, suggesting that approaches for further strengthening of the γδT cell response must be explored." (PMID 26942051, 2016).
cancer (continued). "The results showed that papaya extract significantly inhibited growth of cancer cells and down-regulated the expression of pro-inflammatory cytokines IL-2 and IL-4." (PMID 27769229, 2016). "The patient exhibited intrinsic refractoriness to sequential conventional therapies, including pazopanib, everolimus, and high-dose interleukin-2, resulting in rapid multiorgan dissemination of cancer cells after pulmonary metastectomy." (PMID 27139883, 2016). "In various human cancers malignant cells and host infiltrating cells express and secrete a range of Th1, Th2, and Th17 cytokines (IL-1β, IL-2, IL-4, IL-6, IL-10, IL-17, and IFN-γ) and TGF-β." (PMID 27777963, 2016). "It has not been extensively evaluated for killing function in combination with zoledronate and IL-2 in a range of cancer types expressing GD2." (PMID 26942051, 2016). "Several clinical trials have assessed the effects of IL-2 administration on activation and expansion of NK cells in patients with cancer." (PMID 27807435, 2016). "The essential role of high-dose IL-2 in cancer has now been widely discussed, especially because IL-2 is suspected to optimize all stages of CD8+ T cell response, including primary expansion, contraction, memory generation, and secondary expansion." (PMID 27306834, 2016). "For example, in CTLL-2 cells (cytotoxic T cells), IL-2 increased ZHX1 gene expression and CTLL-2 proliferation, and in malignant breast cancer, an elevated ZHX1 level was associated with cancer cell invasion." (PMID 27835650, 2016). "Our findings that excessive production of IL-2 by Tconvs in response to SA-4-1BBL costimulation is both necessary and sufficient in overcoming Treg suppression may have significant implications for treatment of diseases such as cancer, that are associated with an imbalance between Tconvs and Tregs." (PMID 27049955, 2016). "In mice, addition of IL-2 to experimental cancer vaccines can greatly increase the therapeutic efficacy." (PMID 27660710, 2016). "Intriguingly, patients receiving IL-2 immunotherapy as cancer treatment also feature a splenic enlargement." (PMID 26731275, 2016). "Cytokines themselves such as type I interferon and IL-2 have been extensively applied for the treatment of cancer in a variety of studies and as a part of standard of care therapies." (PMID 28536388, 2016). "A number of clinical trials have already demonstrated that treating cancer patients with a combination of zoledronate and low dose IL-2 can lead to objective clinical responses in those patients where γδT cell expansion is achieved." (PMID 26942051, 2016). "IL-2 has been shown to enhance a T-cell response in animal models of cancer but its’ systemic application has come with a plethora of toxicities." (PMID 28536388, 2016). "Our previous studies found that LaSota/IL2 has a potential immunotherapy and oncolytic therapy for cancers, but the optimal insertion site for IL2 expression remains to be further investigated." (PMID 27736965, 2016). "One distinctive dynamic feature that we observed under low IL-2 is that primary NK cells generally assumed less contacts with the target cancer cells, as compared to that under high IL-2." (PMID 27323411, 2016). "The amount of activated immune cells in peripheral blood correlates with the survival rate of patients, thus the combined applications of IL-2 and GM-CSF were regarded as a promising strategy for cancer immunotherapy." (PMID 26850448, 2016). "Among these various Th subpopulations, the Th1 subset that produces interferon-gamma (IFN-γ), tumor necrosis factor-alpha (TNF-α) and interleukine-2 (IL-2), plays a clear antitumor role by orchestrating cell-mediated immunity against cancer cells." (PMID 26350591, 2015). "Interleukin-2 is a cytokine that stimulates the body’s immune system to recognize, target, and destroy cancer cells; it differs from conventional chemotherapy, which works by killing cancer cells directly." (PMID 26557408, 2015).
cancer (continued). "In a similar setting, NK cells obtained prior to transplant and activated with IL-2 for 6 days were infused into 12 patients with advanced cancer and post-BMT pancytopenia." (PMID 26029215, 2015). "Interleukin-2 was given as pulse in cancer immunotherapy because it is a potent immunomodulator that can induce antitumor activity." (PMID 26078967, 2015). "Cytokines have been applied in cancer immunotherapy for many years, of which IL-2 was approved by the U.S. Food and Drug Administration (FDA) for the treatment of patients with metastatic melanoma." (PMID 25955647, 2015). "Several clinical trials for cancer are currently using IL-2 covalently attached to antibodies that are targeted to molecules enhancing their tumor-specific distribution, e.g. tenascin C, fibronectin and DNA/histones." (PMID 25457307, 2015). "Previous studies have shown that the administration of HD IL-2 can expand the population of Tregs in cancer patients." (PMID 26793191, 2015). "Over the last decade, a number of interleukins (IL), including IL-2, IL-7, IL-12, IL-18 and IL-21, have entered clinical trials for patients at the advanced cancer stage." (PMID 25590298, 2015). "IL-2 stimulates proliferation of effector cells that kill cancer cells but it also plays an important role in the maintenance of regulatory T (Treg) in the periphery that suppresses the immune response." (PMID 25955647, 2015). "For example, treatment with interleukin-2 (IL-2) or interferon-γ (IFN)-γ in patients with cancer is accompanied with depressive symptoms." (PMID 25705518, 2015). "Aging is also associated with progressive decline in T cell functions, including decreased response to various antigens, and production of IL-2, and defect in signalling pathway resulting in the increase in frequency of cancer." (PMID 26294906, 2015). "Cytokines such as interleukin-2 (IL-2) and granulocyte-macrophage colony-stimulating factor (GM-CSF) have been used as adjuvants in cancer vaccines." (PMID 26336989, 2015). "A limitation of high-dose IL-2 therapy in cancers is IL-2-related development of life-threatening toxicity and its short life in systemic delivery." (PMID 25322151, 2014). "This inflammatory environment enhances NK cell activity in patients with superficial bladder cancer and in mouse models of this cancer, and it is known that NK cells are strongly stimulated by IL-2 to differentiate into lymphokine-activated killer cells." (PMID 24466345, 2014). "Recombinant IL-2 has been established as an anti-cancer drug, but because of the dual function of both enhancing and downregulating immune responses, modified IL-2 with less specificity for Treg has been developed." (PMID 24276591, 2014). "At our cancer center we administer IL-2 on the general oncology in-patient service, but have the ability to administer phenylephrine and place patients on continuous cardiac monitoring when needed." (PMID 24855563, 2014). "rhIFNα2b is combined with ribavirin, lamivudine, or adevofir on hepatitis treatment and combined with cytarabin, vinblastine, 5-fluorouracil, tamoxifen, or interleukin-2 on cancer treatment." (PMID 24741445, 2014). "Despite the fact that long-term disease-free survival is seen in some patients, there are only approximately 100 cancer centers in the US that offer high-dose IL-2 because of concerns about toxicity, cost and doubts about efficacy." (PMID 24855563, 2014). "Cancer immunotherapy, such as HD IL-2, consistently delivers durable long term, therapy-free responses." (PMID 25031835, 2014). "As expected, some cytokines showed significant differences between healthy donors and pretreated cancer patients (IL-1β, IL-2, IL-6, TNF-α, and MCP-1)." (PMID 24800238, 2014). "Several members of the common gamma chain (gc) cytokine family are already approved (IL-2) or actively being developed as vaccine adjuvants and cancer immunotherapies." (PMID 25411639, 2014).
cancer (continued). "Our data also reveal that lower IFN-γ production and increased IL-2 production correlated with increased coinhibitory molecule expression in the cancer model." (PMID 24796533, 2014). "The first clinical use of IL-2, but at high doses of about 6–7.2 × 105 IU/kg/dose every 8 h, was aimed at augmenting the immune responses against cancer." (PMID 25322151, 2014). "Our group has recently reported promising examples of therapeutic activity in cancer patients for anti-tenascin-C antibodies, armed with interleukin-2 or with iodine-131." (PMID 24950200, 2014). "High-dose IL-2 therapy of cancers has been somewhat disappointing as only 5%–10% of patients have a long-lasting complete remission." (PMID 25322151, 2014). "The demonstrated potency of TBP-TALEs in synergizing with other VP64 activators to selectively switch on the expression of immunoregulatory genes such as IL-2 and GM-CSF has direct implications for targeted cancer immunotherapy and other similar applications." (PMID 24755922, 2014). "This unique collaboration between physicians, patients, and industry seeks to foster communication, information sharing and innovation regarding HD IL-2’s place in cancer immunotherapy research in a rapidly changing environment." (PMID 25562142, 2014). "IL-2 has been extensively studied in cancer patients and overall yielded unexpectedly few clinical responses as a single agent, likely due to simultaneous induction of regulatory T cells, which can limit NK cell responses." (PMID 25054077, 2014). "Nevertheless,preferential expansion of the CD56bright NK cell subset has also beenobserved following infusion of a low dose of IL-2 to patients with advanced cancers." (PMID 23874793, 2013). "Apart from counteracting VEGF-related IL-2 resistance, EPO controlled cancer growth and reduced the toxicity of IL-2." (PMID 23305401, 2013). "In this context, IL-15 has been suggested to be a substitute for IL-2 as a vaccine adjuvant in the prevention of cancer and infectious diseases." (PMID 24391824, 2013). "One study of IL-2 used in an adjuvant setting as local inhalation therapy for carcinoma reported that 2 of 7 treated dogs achieved full remission for more than a year (29%)." (PMID 23927575, 2013). "We provide clear evidence for an increased expansion of naïve Treg cells particularly post IL-2 therapy as a major mechanism of overall Treg-cell expansion in these cancer patients." (PMID 22276195, 2012). "Many pathways were perturbed in almost all the cancers, with p-value less than 0.01: IL-3 pathway, IL-2 pathway, TNF-alpha Pathway EGFR1 pathway, TGF-beta receptor pathway, Alpha6 Beta4 Integrin pathway, and B Cell Receptor pathway." (PMID 22536907, 2012). "Functional relationship analysis identified upregulation of developmental pathways and downregulation of transcription regulation processes and Toll-Like Receptor (TLR), Interleukin-2 and cancer pathways." (PMID 22260314, 2012). "The potent immunostimulatory effect of systemic IL-2 in advanced cancer patients has been originally demonstrated by the seminal work of Rosenberg and collaborators." (PMID 22319542, 2012). "Since then, several clinical trials based on IL-2 administration have been carried out in different cohorts of cancer patients, mainly including melanoma, renal cell carcinoma, neuroblastoma, breast cancer, and several hematologic malignancies." (PMID 22319542, 2012). "In IL-2 treated cancer patients a further Treg-cell expansion was described, yet, the mechanism of expansion is still elusive." (PMID 22276195, 2012). "Hopeful findings were then applied clinically with IL-2 injection for advanced cancers, and immunotherapy was expected to be a new treatment strategy for cancer." (PMID 22422103, 2012). "Higher frequencies of T-cell receptor excision circles in naïve Treg cells indicate IL-2 dependent thymic generation of naïve Treg cells as a mechanism leading to increased frequencies of Treg cells post IL-2 treatment in cancer patients." (PMID 22276195, 2012).
cancer (continued). "The cytotoxic antitumor capabilities induced in lymphocytes by IL-2 make it a potential cancer immunotherapeutic agent." (PMID 22778725, 2012). "Other cancer immunotherapies have included immunostimulatory cytokines such as IL-2 and IFN-α, as well as antibodies against tumor antigens, for use as adjuvants in combination with chemotherapy or cancer vaccines." (PMID 22927846, 2012). "To date, multiple studies have demonstrated regression of metastatic disease following systemic IL-2 treatment in some cancers." (PMID 22778725, 2012). "Pilot studies of adoptive transfer of IL-2-activated NK cells have demonstrated responses in a wide variety of malignancies." (PMID 22279576, 2012). "IL-15 is also one of several cytokines structurally similar to IL-2 that signal through the γc receptor subunit and have recently entered clinical investigation for cancer and hematologic malignancies." (PMID 24213115, 2011). "The introduction of cytokines, in particular interleukin-2 (IL-2), for cancer treatment was a major clinical effort that had modest success." (PMID 22162711, 2011). "CD8+ T cell expansion has been reported to occur when these cells are exposed to increased IL-2 levels or during adoptive cancer immunotherapy using antigen-specific CD8+ T cells in the presence of IL-2-sufficient CD4+ T cells." (PMID 21423804, 2011). "Usually immune clinical cancer treatment involves the use of high cytokine dose, reaching in the case of IL-2 dose near or superior to 18000000 IU." (PMID 22084730, 2011). "Notwithstanding this well-established role in cancer, we demonstrate the additional role of this miRNA in directly targeting chicken IL-2 through reporter and biochemical assays." (PMID 20441582, 2010). "From this small pilot study we can conclude that our full length Her2-pDNA, administered together with GM-CSF and IL-2, is safe, well tolerated and can induce both antibody and T-cell responses in advanced stage cancer patients." (PMID 20529245, 2010). "The currently 287 ongoing or closed gene therapy protocols utilizing Ad vectors for cancer treatment include 20 protocols with IL-2, and 11 protocols with CD40L as therapeutic gene, respectively." (PMID 20670430, 2010). "It has been shown that GM-CSF-secreting tumor cell immunotherapy with VEFG-blocking agents prolonged survival of cancer bearing mice, while IL-2 and GM-CSF can have a suppressive effect on Tregs." (PMID 21318181, 2010). "Two IL2-based immunocytokines (L19-IL2 and F16–IL2) are currently being investigated in phase I and phase II clinical trials in patients with cancer." (PMID 20736949, 2010). "Outpatient low-dose IL-2 has, therefore, been previously used to enhance cancer patients’ immune response to mAbs with little toxicity." (PMID 19920829, 2010). "For these reasons, cytokine therapies of malignant tumors using IL-2, IL-12, and IFN-γ have been investigated extensively in experimental and clinical studies." (PMID 19292900, 2009). "This is one of the Macromed's products, which is a novel, peritumoral, injectable depot formulation of interleukin-2 (IL-2) for cancer immunotherapy using Regel drug delivery system." (PMID 20490289, 2009). "Although over 20 cytokines have been developed for the treatment of cancer, only IL-2, IFN-α and TNF-α have been approved in the US and/or Europe for immunologic anti-cancer therapy." (PMID 19175928, 2009). "Traditionally, interleukin-2 and interferon alfa have been administered in this setting, with high toxicity and limited improvement in cancer-specific survival." (PMID 19478895, 2009). "The expression of IL-2R on keratinocytes and the IL-2 secretion has been reported in different phases of cancer cell development." (PMID 19689792, 2009). "This study showed that IL-2 treatment leads to a significant increase of immunological parameters, concomitantly with a reduction in vasculature, providing new insight into the cancer mechanisms mediated by IL-2." (PMID 19935800, 2009).